TRIB3 (tribbles pseudokinase 3)
Diseases named in the same sentence as TRIB3 in open-access papers (continued):
Sharing a sentence is not in itself a finding about the gene and the disease.
pulmonary arterial hypertension (2 papers, 2020 to 2023). Pulmonary arterial hypertension (PAH) is a group of diseases characterized by mean pulmonary artery pressure >20 mmHg and elevated pulmonary arterial resistance leading to right heart failure. "PPARγ, which could be regulated by TRIB3, was reported that inhibited TGF-β signaling and acted as a link between pro-proliferative TGF-β and anti-proliferative bone morphogenetic protein 2 (BMP2) signalings in vascular smooth muscle cells and inhibited pulmonary arterial hypertension." (PMID 33192545, 2020).
acute leukemia (1 paper, 2022). A clonal (malignant) hematopoietic disorder with an acute onset, affecting the bone marrow and the peripheral blood. "The stress pseudo-kinase TRIB3 is also implicated in acute leukemias, and IZKF2 is a well-known transcription factor in normal and malignant hematopoietic cells." (PMID 35371997, 2022).
anaemia (1 paper, 2017). "It would be therefore also interesting to analyse if Trib3 deficiency affects the balance between erythropoiesis and megakaryocytopoiesis under conditions of experimental-induced anaemia." (PMID 28751721, 2017).
asthma (1 paper, 2021). "In COPD patients, TRIB3 showed logFC = -0.32 and p<0.001 and, for asthma patients, TRIB3 were reduced in both datasets (logFC = -0.3 and -0.4, p<0.05)." (PMID 33532126, 2021). "In conclusion, we show that lung gene expression of TRIB3, a protein predicted to interact with the nucleocapsid protein and the RNA-dependent RNA polymerase of HCoVs, decreases in COPD, asthma and males during aging." (PMID 33532126, 2021).
breast adenocarcinoma (1 paper, 2019). "The grade of FOXO1 expression was correlated with the TRIB3 expression in tumor tissues based on immunohistochemistry analysis of human tumor tissue microarrays of breast adenocarcinoma." (PMID 31844113, 2019). "Using human tumor tissue microarrays of breast adenocarcinoma, higher TRIB3 levels were observed in tumor tissues than in adjacent nontumor tissues." (PMID 31844113, 2019). "Using human tissue microarrays of breast adenocarcinoma, SOX2 expression was determined to be higher in tumor tissues than in adjacent nontumor tissues, and the expression level of TRIB3 correlated with the expression level of SOX2 in tumor tissues." (PMID 31844113, 2019).
carotid atherosclerosis (1 paper, 2012). A thickening and loss of elasticity of the walls of carotid arteries that occur with formation of atherosclerotic plaques. "In the present study, we aimed to investigate the role of obestatin in MetS and carotid atherosclerosis under the background of TRIB3 Q84R polymorphism by case-control study." (PMID 23245314, 2012). "However, this study provides new insights into the potential associations of decreased obestatin with TRIB3 Q84R polymorphism, MetS and carotid atherosclerosis." (PMID 23245314, 2012). "Aims to investigate whether the prevalent TRIB3 Q84R polymorphism has profound implications for alterations of serum obestatin and what effect obestatin exerts on carotid atherosclerosis." (PMID 23245314, 2012).
cerebrovascular disease (1 paper, 2022). "We found that the variable number of tandem repeats of TRIB3 promoter was significantly correlated with the risk of cerebrovascular disease and diabetic retinopathy." (PMID 36105108, 2022). "By exploring the relationship between TRIB3 promoter 33bp VNTR and common complications of T2DM, our study found that TRIB3 promoter 33bp VNTR was significantly associated with the risk of cerebrovascular diseases and diabetic retinopathy for the first time." (PMID 36105108, 2022). "In our findings, we found for the first time that TRIB3 promoter 33bp VNTR is closely associated with the risk of cerebrovascular diseases in T2DM patients." (PMID 36105108, 2022). "Although the TRIB3 promoter 33bp VNTR was found to be significantly associated with cerebrovascular disease in our findings, surprisingly, this VNTR was not significantly correlated with cardiovascular disease." (PMID 36105108, 2022). "Although TRIB3 is implicated in both T2DM and vascular disease, the association between TRIB3 VNTR and diabetic cerebrovascular disease has not been reported." (PMID 36105108, 2022).
Cirrhosis (1 paper, 2020). A chronic disorder of the liver in which liver tissue becomes scarred and is partially replaced by regenerative nodules and fibrotic tissue resulting in loss of liver function. "Recently, it has been reported that high levels of tribbles pseudokinase 3 (TRIB3) and p62 were positively correlated in livers of patients with cirrhosis." (PMID 32724454, 2020).
colorectal adenocarcinoma (1 paper, 2021). The most common type of colorectal carcinoma. "In human tumor xenografts with HT-29 colorectal adenocarcinoma cells, TRIB3 expression pattern was proximal to a region of cell death, localized to a periapoptotic region." (PMID 34198908, 2021). "In HT-29 colorectal adenocarcinoma cells subjected to hypoxia, TRIB3 was upregulated at the transcript and protein level, suggesting TRIB3 could be regulated in CRC by classical hypoxia-related transcription factors, such as HIF1α." (PMID 34198908, 2021).
COVID-19 (1 paper, 2021). A disease caused by infection with severe acute respiratory syndrome coronavirus 2. "TRIB3 expression was decreased in lung comorbidities associated with COVID-19 severity." (PMID 33532126, 2021). "This study provides insights into aging and COVID-19 based on the transcriptional profile of the aging lung and reveals a potential role for TRIB3, surfactant metabolism, and mitotic cell cycle." (PMID 33532126, 2021). "Considering the need for drugs to treat COVID-19, the α-hydroxylinoleic acid (ABTL0812) induces the expression of TRIB3 by inhibiting the PI3K/AKT/mTOR axis and promoting autophagy cell death in cancer." (PMID 33532126, 2021).
diabetic retinopathy (1 paper, 2022). "TRIB3 dynamically changes with treatment and thus modifies the effect on diabetic retinopathy risk." (PMID 36105108, 2022). "Further research is warranted to confirm whether TRIB3 VNTR affects blood pressure, the risk of diabetic cerebrovascular disease and diabetic retinopathy and its involvement in the ACEI/ARB pathway." (PMID 36105108, 2022).
diffuse large B-cell lymphoma (1 paper, 2020). "To examine the role of TRIB3 in lymphomagenesis, we searched the Oncomine database and found that TRIB3 expression was elevated in peripheral T-cell lymphoma (PTCL) and diffuse large B-cell lymphoma (DLBCL) compared to normal lymphocytes." (PMID 33298911, 2020).
endothelial dysfunction (1 paper, 2020). In vascular diseases, endothelial dysfunction is a systemic pathological state of the endothelium (the inner lining of blood vessels) and can be broadly defined as an imbalance between vasodilating and vasoconstricting substances produced by (or acting on) the endothelium. "Moreover, TRIB3 knockdown caused significant improvement in Akt and eNOS phosphorylations and otherwise a reduction of ERK1/2 activation in PAECs after hypoxia, suggesting that TRIB3 mediates hypoxia-induced VIR and endothelial dysfunction." (PMID 33192545, 2020).
epilepsy (1 paper, 2019). A brain disorder characterized by episodes of abnormally increased neuronal discharge resulting in transient episodes of sensory or motor neurological dysfunction, or psychic dysfunction. "Further studies would be of help in clarifying the mechanisms for the role of TRIB3 in neuronal apoptosis for a better understanding of the molecular mechanisms underlying epilepsy-related brain damage in vivo." (PMID 31191318, 2019). "Our findings suggest that TRIB3 and its regulatory pathways be considered potential and promising therapeutic targets for the treatment of epilepsy." (PMID 31191318, 2019). "Collectively, epilepsy induces ER stress and overexpression of TRIB3." (PMID 31191318, 2019). "The knockdown of TRIB3 effectively protects against neuronal apoptosis in vitro, suggesting that TRIB3 may be a potential therapeutic target for the treatment of epilepsy." (PMID 31191318, 2019). "In the present study, we explored the role of TRIB3 in an epilepsy paradigm." (PMID 31191318, 2019). "However, the role of TRIB3 in epilepsy and epilepsy-related brain injury remains controversial." (PMID 31191318, 2019). "In the present study, we used a kainic acid (KA) (10 mg/kg)-induced rat seizure model to investigate the role of TRIB3 and the relationship between TRIB3 and AKT in childhood epilepsy-related neuronal apoptosis of the cortex." (PMID 31191318, 2019).
esophageal squamous cell carcinoma (1 paper, 2020). Esophageal squamous cell carcinoma (ESCC) is a type of esophageal carcinoma (EC) that can affect any part of the esophagus, but is usually located in the upper or middle third. "In esophageal squamous cell carcinoma (ESCC), upregulation of TRIB3 conferred radio-resistance by β-TrCP-mediated TAZ ubiquitination and degradation and interaction with TAZ in vitro and in vivo." (PMID 32874132, 2020).
Ewing sarcoma (1 paper, 2025). A small round cell tumor that lacks morphologic, immunohistochemical, and electron microscopic evidence of neuroectodermal differentiation. "For example, TRIB3 is a direct ATF4 target in Ewing sarcoma and is elevated in FP-RMS tumors relative to normal tissue and fusion-negative RMS." (PMID 40508013, 2025).
gastric disease (1 paper, 2021). "Overall, the protein expression trends of TRIB3 among different gastric disease were GS > IM-GA > EGC > AGC and NCG > CG." (PMID 34957220, 2021). "As far as we know, this is the first study assessing the expression trend of TRIB3 and FABP1 in the dynamic process of gastric disease development, and also the first report correlating TRIB3 with FABP1." (PMID 34957220, 2021). "In conclusion, the protein expressions of TRIB3 and FABP1 gradually decreased with the gastric disease progress, and was positively correlated." (PMID 34957220, 2021). "In this study, we elucidated the protein expression of TRIB3 and FABP1 in different stages of gastric disease, and identified the correlation between their expressions." (PMID 34957220, 2021).
Hepatic steatosis (1 paper, 2024). Steatosis is a term used to denote lipid accumulation within hepatocytes. "In the context of reduced hepatic steatosis and adipose tissue macrophage infiltration, Trib3 KO mice maintained lower circulating insulin levels and exhibited increased insulin-dependent skeletal muscle glucose uptake than did control mice." (PMID 39623091, 2024). "The hepatic steatosis and adipocyte hypertrophy observed in the control mice fed a 60% HFD were alleviated in the Trib3 KO mice." (PMID 39623091, 2024).
insulinoma (1 paper, 2021). "Such FFA increases accompany 3-fold rises in pseudokinase 3 (TRIB3) expression and reduce the Akt phosphorylation status in both the human liver and in insulinoma cell lines." (PMID 34503515, 2021).
laryngeal carcinoma (1 paper, 2025). Carcinoma that arises from the laryngeal epithelium. "Yet, additional research is necessary to illuminate if TRIB3 can be used as a target for immunotherapy of laryngeal cancer." (PMID 39869954, 2025).
lumbar disc degeneration (1 paper, 2024). "ANGPTL4, IGFBP3, PTGES in chondrocytes 4 and TRIB3, GDF15, TNFRSF10B in chondrocytes 5 may play an important role in the lumbar disc degeneration process." (PMID 38654287, 2024). "Some genes are widespread in chondrocyte 4, and chondrocyte 5 may play an important role in the process of lumbar disc degeneration together with the Wnt/Ca2+signaling pathway, such as ANGPTL4, PTGES, IGFBP3, GDF15, TRIB3, and TNFRSF10B." (PMID 38654287, 2024).
metastatic melanoma (1 paper, 2023). A melanoma that has spread from its primary site to another anatomic site. "Compared to primary samples, the proteins of TRIB3 and SLC12A9 were highly expressed in metastatic melanoma." (PMID 37268878, 2023).
myocardial ischemia (1 paper, 2022). A disorder of cardiac function caused by insufficient blood flow to the muscle tissue of the heart. "For instance, the TRIB3 R84 variant significantly increases the risk of T2DM and is related to earlier the onset age of myocardial ischemia in T2DM patients with myocardial ischemia." (PMID 36105108, 2022).
ovarian epithelial malignant tumors (1 paper, 2020). "The expression level of TRIB3 was higher in ovarian epithelial malignant tumors as compared to other groups." (PMID 32874132, 2020).
parasitic infections (1 paper, 2025). "Meanwhile, genes related to cancer metastasis, such as Tns4, Neu1, Serpina10, and Trib3 (54, –, 57), as well as Mcpt1 and Mcpt2, which are associated with parasitic infections, were significantly upregulated after infection." (PMID 39727670, 2025).
psoriasis (1 paper, 2025). An autoimmune condition characterized by red, well-delineated plaques with silvery scales that are usually on the extensor surfaces and scalp. "P. clypearia may ameliorate inflammation in psoriasis mice by modulating genes such as Hspa1a, Hspa1b, mt-Nd4l, mt-Nd5, mt-Nd6, Bcl2, Asns, Trib3, and associated pathways related to energy metabolism, cell growth, and apoptosis." (PMID 41385507, 2025). "The results indicated that P. clypearia may affect the energy metabolism, cell growth and apoptosis by regulating genes such as Hspa1a, Hspa1b, mt-Nd4l, mt-Nd5, mt-Nd6, Bcl-2, Asns, Trib3, GzmA, CTSG, etc, thereby mitigating psoriasis-related inflammation." (PMID 41385507, 2025).
rheumatoid arthritis (1 paper, 2022). A chronic, systemic autoimmune disorder characterized by inflammation in the synovial membranes and articular surfaces. "The analysis showed that TRIB3 was related to humoral immune responses, the collagen-containing extracellular matrix, serine hydrolase activity, and rheumatoid arthritis." (PMID 35726370, 2022).
sarcoma (1 paper, 2025). A usually aggressive malignant neoplasm of the soft tissue or bone. "Thus, TRIB3 appears to function as a broadly activated component of sarcoma stress adaptation rather than as a marker unique to FP-RMS." (PMID 40508013, 2025).
serous ovarian cancer (1 paper, 2020). "KM-plot website analysis showed that serous ovarian cancer patients with high expression levels of TRIB3 had significantly shorter survival times compared to patients with low expression levels of TRIB3 (P = 0.0035)." (PMID 32874132, 2020).
uremia (1 paper, 2025). A clinical syndrome associated with the retention of renal waste products or uremic toxins in the blood. "Subtotal nephrectomy and STZ, combined with a diabetic diet, caused uremia in ApoE-KO mice and in double-KO TRIB3 and ApoE mice (ApoE/TRIB3 KO)." (PMID 39932798, 2025).
cancer (101 papers, 2009 to 2025). A tumor composed of atypical neoplastic, often pleomorphic cells that invade other tissues. "In conclusion, PB can targeting TRIB3 and disrupting the cell cycle signaling pathway in BC, offering deeper insights into the mechanisms underlying PB’s anti-cancer effects." (PMID 39881875, 2024). "TRIB3 protein belongs to the pseudokinase family and is closely associated with the onset of various cancers." (PMID 38235126, 2023). "Compelling findings provided evidence that TRIB3 linked stress signals are capable of promoting tumor initiation and progression by supporting cancer stemness, which is coordinated with elevated FOXO1 and AKT1 axis." (PMID 35473511, 2022). "Upregulated TRIB3 was associated with increased drug sensitivity of cancer cells to Imiquimod, Vismodegib and umbralisib." (PMID 34745224, 2021). "Several metabolic risk factors, including insulin and IGF‐1‐enhanced TRIB3 expression in a diversity of human cancer cells." (PMID 27038142, 2016). "In a recent report 3, Hu and his colleagues have verified that TRIB3, a stress‐induced protein, links metabolic risk factors to cancer development and progression via interacting with SQSTM1, a selective autophagy receptor." (PMID 27038142, 2016). "However, in the current version of The Cancer Genome Atlas Research Network (TCGA) that comprises cancer samples for 33 different cancer types (last access January 2021) TRIB3 is mutated in 1.28% of cancer samples." (PMID 33920424, 2021). "Importantly, dysregulation of TRIB3 has been associated with different pathological conditions including cancer development." (PMID 34771470, 2021). "TRIB3 is a stressor sensor involved in the alterations of the cellular microenvironment and various stress-inducing factors, including insulin, glucose deficiency, and the accumulation of misfolded proteins within the endoplasmic reticulum, and it has a tumorigenic role in different cancers." (PMID 39941896, 2025). "Moreover, TRIB3 has been implicated in the pathogenesis of several diseases, including type 2 diabetes and its complications, Parkinson’s disease and several types of cancer." (PMID 32745133, 2020). "This underscores the intricate interplay between TRIB3 expression and cancer progression, further reflecting the complexity of hypoxia’s impact on prognosis." (PMID 40322886, 2025). "Tribbles homolog 3 (TRIB3) is one such pseudokinase with significant implications in cancer biology." (PMID 40508013, 2025). "Since AA restriction upregulates ATF4 in activated T cells and TRIB3 overexpression is consistently observed across various cancers, we employed the 2xAARE system from the TRIB3 gene to create an ATF4-based strategy that restricts CAR expression to the TME." (PMID 40335738, 2025). "Despite these insights into its role in cancer, the specific effect of TRIB3 on HNSCC has remained unclear." (PMID 38429254, 2024). "With mounting recognition, TRIB3 has assumed a role as a promoter of tumorigenesis across diverse cancer types." (PMID 38429254, 2024). "Remarkably, consistent with these findings, the knockdown of TRIB3 significantly suppressed cancer development in a subcutaneous HNSCC xenograft tumor model." (PMID 38429254, 2024). "Cancer cells express proteins such as sortilin, tribbles homolog 3 protein (TRIB3), and ubiquitin specific peptidase 22 (USP22), which suppress EGFR degradation via EGFR stabilization, and their knockdown inhibits cancer cells." (PMID 38745775, 2024). "TAMs synthesize the cytokine TGF-β to enhance HIF1α expression, leading to an increase in Tribbles pseudokinase 3 (TRIB3) within cancer cells." (PMID 39201782, 2024). "Numerous studies have identified TRIB3 as an important tumor marker and therapeutic target, promoting cancer progression by interacting with various target proteins across multiple tumor types." (PMID 39881875, 2024). "Tribbles pseudokinase 3 (TRIB3) has been identified recently as a novel oncogene in several cancers." (PMID 38429254, 2024).